RABL2A (RAB, member of RAS oncogene family like 2A)
Description:
Small GTPase that plays an essential role in male fertility, sperm intra-flagellar transport, and tail assembly. Binds, in a GTP-regulated manner, to a specific set of effector proteins including key proteins involved in cilia development and function and delivers them into the growing sperm tail.
Tractability: PROTAC: ubiquitination databases record sites on it.
Gene: Protein-coding gene on chromosome 2 (113,627,215 to 113,643,407, forward strand). Ensembl gene ENSG00000144134.
Subcellular location (Human Protein Atlas): Basal body; Centrosome; Vesicles
Gene Ontology:
Molecular function: G protein activity; GTPase activity; GTP binding
Biological process: cilium assembly; microtubule-based movement
Cellular component: cilium
Genetic constraint (gnomAD): Loss-of-function variants: 14 observed, 22.49 expected, observed/expected ratio (o/e) 0.62, 90% interval 0.41 to 0.97. The upper end of that interval is the gene's LOEUF score, 0.97, which puts it in group 4 of 6, group 1 being the genes least tolerant of losing a copy. Missense variants: 141 observed, 200.82 expected, observed/expected ratio (o/e) 0.7, 90% interval 0.61 to 0.81. Synonymous variants: 61 observed, 74.85 expected, observed/expected ratio (o/e) 0.81, 90% interval 0.66 to 1.01.
Homologues: Orthologues: chimpanzee RABL2A (97% identical), macaque RABL2B (96% identical), macaque RABL2B (95% identical), dog RABL2B (86% identical), rat Rabl2 (83% identical), mouse Rabl2 (81% identical), tropical clawed frog rabl2b (73% identical), zebrafish rabl2 (70% identical), chimpanzee RABL2B (59% identical). Paralogues in human: RABL2B (99% identical), RAB14 (25% identical), RAB5C (25% identical), RAB11A (24% identical), RAB11B (24% identical), RAB36 (24% identical), RAB5A (24% identical), RAB24 (24% identical), RAB33A (24% identical), RAB12 (24% identical), RAB22A (24% identical), RAB30 (24% identical), and 56 more.
Diseases named in the same sentence as RABL2A in open-access papers:
RABL2A is named in the same sentence as 4 diseases in open-access papers, as found by Europe PMC text mining. Sharing a sentence is not in itself a finding about the gene and the disease. The quoted sentences say what the papers report.
diabetes (1 paper, 2020). "We found that RABL2A had significantly lower expression in PC patients with diabetes." (PMID 32759795, 2020).
male infertility (1 paper, 2022). The inability of the male to effect fertilization of an ovum after a specified period of unprotected intercourse. "Among the other validated hits were proteins involved in the ubiquitin proteasome system (STAMBP and MYLIP), transcription (MTA1, PKNOX2), translation (EIF4E3), male infertility (RABL2A, DAZAP1), and virus-induced oncogenesis (MTA1)." (PMID 35452674, 2022).
pancreatitis (1 paper, 2020). Inflammation of the pancreas. "The expression of RABL2A was significantly reduced in PDACs from diabetic patients, whereas RAB26 was significantly downregulated in patients with pancreatitis." (PMID 32759795, 2020). "The expression of RABL2A was significantly reduced in PDAC from diabetic patients, whereas RAB26 was significantly lower in pancreatitis patients." (PMID 32759795, 2020).
RABL2A also shares sentences with these, for which no sentence is quoted: cancer (1 paper).